DYSF (dysferlin)
Diseases named in the same sentence as DYSF in open-access papers (continued):
Sharing a sentence is not in itself a finding about the gene and the disease.
Hyperglycemia (1 paper, 2020). An increased concentration of glucose in the blood. "LVH is associated with fibrosis, which results in elevated dysferlin that functions in cardiac extracellular membrane repair, and TGF-β1 is increased in hyperglycemia in diabetic models." (PMID 32346034, 2020).
immune deficiencies (1 paper, 2017). "Furthermore, it is possible that accompanying immune deficiencies observed in the SJL/J mice contribute to disease progression, rather than the loss of dysferlin itself." (PMID 28320887, 2017).
kidney cancer (1 paper, 2022). Primary or metastatic malignant neoplasm involving the kidney. "Using genevisible data bank, Dysferlin is mainly detected in various endothelial tissues, leukemia, and kidney cancer." (PMID 35330493, 2022).
liposarcoma (1 paper, 2014). A usually painless malignant tumor that arises from adipose tissue. "Specifically, it was found that the mice with the mutation in Dystrophin, Dysferlin and Calpain-3 were susceptible to spontaneous formation of rhabdomyo-, fibro-and liposarcomas derived from skeletal muscle tissue 1–4 (reviewed in 5)." (PMID 24341522, 2014).
lung carcinoma (1 paper, 2022). "Fusion of DYSF with the ALK gene has been found to be associated with advanced lung cancer." (PMID 35923697, 2022). "The expressions of EMR3, NCF1, CSF2RB, DYSF, TLR8, and HCK in the lung cancer group were significantly different from those of the control group." (PMID 35923697, 2022).
lysosomal storage disease (1 paper, 2025). A metabolic disorder caused by mutations in proteins critical for lysosomal function, including lysosomal enzymes, lysosomal integral membrane proteins, and proteins involved in the post-translational modification and trafficking of lysosomal proteins. "Another possibility is that dysferlin can facilitate the repair of damaged membranes through the fusion of lysosomes, a key cholesterol‐regulating organelle, through acid sphingomyelinase, which is linked to the Niemann–Pick group of lysosomal storage diseases." (PMID 40814795, 2025).
multiple sclerosis (1 paper, 2018). A progressive autoimmune disorder affecting the central nervous system resulting in demyelination. "DYSF is induced in vitro by TNF-alpha and has also been shown to be up-regulated in the blood vessels of patients with multiple sclerosis representing increased vascularinflammation and a disturbed blood–brain barrier." (PMID 29530068, 2018).
oral squamous cell carcinomas (1 paper, 2022). "Our study describes the neoexpression (Juno) and suppression (catsperD, dysferlin, Fer1L5 and otoferlin) of selected genes in oral squamous cell carcinomas (OSCCs)." (PMID 35330493, 2022).
reticulum cell sarcoma (1 paper, 2011). An antiquated term that refers to a non-Hodgkin lymphoma composed of diffuse infiltrates of large, often anaplastic lymphocytes. "None of the SJL/J mice, which also carry a mutant allele of dysferlin, developed RSC; however, many fewer old mice of this strain were obtained primarily due to fighting and their propensity for other types of cancer, including spontaneous reticulum cell sarcomas." (PMID 21853140, 2011).
schizophrenia (1 paper, 2021). A major psychotic disorder characterized by abnormalities in the perception or expression of reality. "The genes ZNF773, PCNT, and DYSF were assigned the highest weights by the neural network and were thus considered to be the most predictive genes for schizophrenia." (PMID 34535759, 2021).
viral myocarditis (1 paper, 2021). Myocarditis that is caused by an infection with a viral agent. "Defects in dysferlin-mediated repair can be genetically linked (e.g., LGMD2B) or arise during viral myocarditis to exacerbate damage as a cell-cell spread tactic." (PMID 33849525, 2021).
weakness (1 paper, 2024). "In Austria, the most frequent cause of limb-girdle muscular weakness and hereditary myopathy were pathogenic variants in CAPN3, FKRP, ANO5, DYSF, SGCA." (PMID 38758368, 2024).
myopathy (31 papers, 2010 to 2025). A disease of the muscle in which the muscle fibers do not function properly. "Dysferlin encoded by DYSF has been typically implicated in myopathies and found to regulate cell adhesion in monocytes." (PMID 35864995, 2022). "Similar outcomes were seen in the dysferlin-deficient SJL/J mice, a mouse model that develops a spontaneous myopathy phenotype resulting from a splice-site mutation in the DYSF gene." (PMID 34199845, 2021). "LGMD2B is part of the family of dysferlin deficient myopathies inherited as autosomal recessive disorders." (PMID 21816046, 2011). "It is important to recognize these caveats when attempting to draw associations between the pathobiology of this strain and that of dysferlin deficient myopathies." (PMID 20886045, 2010). "Together, these features make SJL/J mice a genetic homologue of human dysferlin deficient myopathies." (PMID 20886045, 2010). "The dysferlin deficient SJL/J mouse strain is commonly used to study dysferlin deficient myopathies." (PMID 20886045, 2010). "Fasudil was selected for evaluation because of the established role of Rho- kinases in macrophage/monocyte activation and the potential involvement of these inflammatory cells in the progression of dysferlin deficient myopathies." (PMID 20886045, 2010). "Our studies, and those of others, clearly identify dysferlin as being required for the control of Ca2+ release in healthy muscle, and that, when missing or mutated, it results in abnormal Ca2+ release that is associated with myopathy." (PMID 41227369, 2025). "As preclinical outcomes for mdx mouse trials were recently assessed, the present paper focuses on a similar standardized evaluation of commonly used behavioral tests in dysferlin deficient SJL/J mice, which have been proposed as an animal model for dysferlin deficient myopathies." (PMID 20886045, 2010). "Chronic treatment with the Rho-kinase inhibitor, fasudil worsened functional outcomes, but also reduced inflammatory cell infiltrates in diseased SJL/J muscle, which suggests that Rho-kinase may have a multifactorial role in dysferlin-deficient myopathy." (PMID 20886045, 2010). "In addition, the data provide pharmacological evidence suggesting that activation of rho-kinase, at least in part, may represent a beneficial compensatory response in dysferlin deficient myopathies." (PMID 20886045, 2010). "Knockout mouse models of dysferlin exhibit a disordered sarcotubular network after injection of glycerol into the skeletal muscle to induce myopathy suggesting that dysferlin also contributes to skeletal muscle t-tubule stability." (PMID 31520263, 2019). "T-tubule abnormalities are seen in multiple myopathic states, including the central nuclear myopathies and dysferlin-mediated myopathies." (PMID 26325203, 2015). "A large proportion of pathological controls with other myopathies (13/21) showed abnormal patterns of dysferlin expression using IH but their dysferlin expression in skeletal muscle and PBM was normal according to WB." (PMID 22194990, 2011). "IH results, on the other hand, were misleading because dysferlin expression was deficient both in patients with mutations in DYSF and in patients with other myopathies." (PMID 22194990, 2011). "Nevertheless, the role of apoptosis, or ROCK, in dysferlin deficient myopathy, has not been well studied, and remains uncertain." (PMID 20886045, 2010). "The genes DES, TNNT1, MYH7, and DYSF were identified as important regulatory genes in both the OMIM and KEGG myopathy pathway." (PMID 40149400, 2025). "Several genes were found to be significantly enriched by simvastatin treatment in primary human muscle cells and were mapped to both OMIM as well as KEGG pathways for myopathy, including DES, TNNT1, MYH7, and DYSF." (PMID 40149400, 2025). "GNE, DYSF, and CAPN3 are the three major genetic contributors to these myopathies in the Indian subcontinent." (PMID 33250842, 2020).
myopathy (continued). "DYSF gene is much larger than some of the other genes such as GNE and CAPN3, the other two most prevalent myopathy forms in this study." (PMID 33250842, 2020). "Tamoxifen might also prove useful in other myopathies where t-tubule defects secondary to increased DNM2 levels contribute to the pathogenesis, such as BIN1-related CNM and caveolin-3 and dysferlin-related myopathies." (PMID 30451843, 2018). "Several authors have described different IH patterns of dysferlin expression in muscle biopsies from patients with different myopathies, but none of them compared this expression with that found in PBM." (PMID 22194990, 2011).
cancer (8 papers, 2011 to 2025). A tumor composed of atypical neoplastic, often pleomorphic cells that invade other tissues. "Some members of ferlins have already been discovered in human cancer: Dysferlin is significantly associated with pancreatic cancer patient survival, while Otoferlin is correlated to renal clear carcinoma and Fer1L5 to lung adenocarcinomas." (PMID 35330493, 2022). "Interestingly, mice lacking dystrophin or dystrophin-associated proteins including dysferlin, α sarcoglycan, calpain-3, and Large form spontaneous malignant tumors with muscle differentiation." (PMID 30575736, 2018). "For some genes (CatsperB, CatsperD, Dysferlin, Fer1L5, Juno), a limited number of published literature referring to cancer is known." (PMID 35330493, 2022). "However, unlike dysferlin, myoferlin has recently also been found to be overexpressed in various human cancers and the altered vesicular trafficking and function of myoferlin has been linked to cancer cell proliferation, metastasis, and resistance to chemotherapy." (PMID 40437073, 2025).
muscular disorders (7 papers, 2018 to 2024). "Dysferlin deficiency in myofibers inhibits sarcolemmal repair, disrupts calcium homeostasis at the T-tubules and alters immune response leading to progressive and debilitating muscular disorders characterized by extremely low regenerative capacity, inflammatory infiltrates and fibro-adipogenesis." (PMID 36402750, 2022). "We discovered novel compound heterozygous mutation of dysferlin and the TOR1A ΔE mutation in the same family, causing two similar but distinct hereditary muscular disorders in siblings." (PMID 34276779, 2021).
tumor (7 papers, 2011 to 2022). "Mice with mutations in the Dystrophin (DMD), Calpain-3 (LGMD2A) or Dysferlin (LGMD2B) genes are susceptible to malignant tumours originating from the skeletal muscles 1–4 (reviewed in 5)." (PMID 24341522, 2014). "Combined loss of dystrophin and dysferlin, as well as dystrophin and calpain-3, leads to accelerated tumor formation." (PMID 21533183, 2011). "As a result of this approach, particularly Juno as a real tumor marker but also four additional genes, namely CatsperD, Dysferlin, Fer1L5, and Otoferlin remain to be useful in characterizing oral malignancies." (PMID 35330493, 2022). "In summary, Dysferlin can be used as target molecule for oral tumor diagnosis, perhaps even in other tumor entities as long as the score for specifities and sensitivities is high enough accompanied by significant differences on its expression level." (PMID 35330493, 2022). "In order to test if dystrophin, dysferlin and calpain-3 have tumor-suppressor effects in vivo, we generated double-mutant mouse lines, i.e. dystrophin-deficient (mdx) mice with additional lack of either dysferlin (Dmd −/− Dysf −/−) or calpain-3 (Dmd −/− Capn3 −/−)." (PMID 21533183, 2011). "Based on the spontaneous occurrence of skeletal muscle-tumors in mice deficient for the so far molecularly unrelated genes dystrophin and dysferlin, we hypothesized that MD-genes in more general might act as tumor suppressors." (PMID 21533183, 2011).
neuromuscular disease (6 papers, 2011 to 2025). "NGS targeting 230 genes causative of neuromuscular diseases revealed two heteroallelic DYSF variants, c.2517del, p.Met840Trpfs*108 (pathogenic) and c.6058C > T, p.Arg2020Cys (VUS)." (PMID 40545540, 2025). "The discovery of previously unreported DYSF mutations not only facilitates further investigation into their pathogenicity but also broadens our understanding of hereditary neuromuscular diseases." (PMID 41040662, 2025).
genetic disorders (5 papers, 2010 to 2025). "Mutations on human genes encoding AAT 19, collagen α−1(II) chain (COL2A1) 20, Niemann-Pick type C1 (NPC1) 21, and dysferlin (DYSF) 22, 23 can cause their misfolding in the ER, leading to degradation by ERQC and various genetic diseases." (PMID 40678220, 2025). "There are six mammalian ferlins (Fer1L1-6), with mutations in FER1L1 (dysferlin) and FER1L2 (otoferlin) linked to inherited diseases in humans." (PMID 20667140, 2010).
autosomal recessive disease (3 papers, 2017 to 2025). Autosomal recessive form of disease. "The mutations in DYSF (MIM∗603009) cause these autosomal recessive diseases." (PMID 33031319, 2020).
blood disorders (2 papers, 2014 to 2017). "To further investigate whether dysferlin on the RBC is a general marker of stress hematopoiesis we investigated other blood disorders for the presence of dysferlin on the RBC membrane with western blot analysis." (PMID 24454878, 2014).
cardiac disease (2 papers, 2021 to 2025). "Mice lacking MG53 or dysferlin do not show overt heart disease at baseline but are vulnerable to cardiac dysfunction under stress conditions." (PMID 33949649, 2021).
infection (1 paper, 2024). The state of being infected such as from the introduction of a foreign agent such as serum, vaccine, antigenic substance or organism. "To illustrate the performance of the COCONUT normalization, we visualized the log2 expression values of commonly used house-keeping genes (ATP6V1B1, and GAPDH) and genes known to be modulated by infection (CEACAM1 and DYSF) as previously shown." (PMID 38817614, 2024). "The pronounced increased expression of genes related to infection (CEACAM1 and DYSF) were not diminished." (PMID 38817614, 2024).
DYSF also shares sentences with these, for which no sentence is quoted: distal anterior compartment myopathy (9 papers); Becker muscular dystrophy (6); autosomal recessive limb-girdle muscular dystrophy (4); degenerative diseases (3); Miyoshi muscular dystrophy 1 (3); myocardial infarction (3); cardiovascular disease (2); caveolinopathies (2); hearing loss (2); hyperlipidemia (2); Hypertension (2); idiopathic inflammatory myopathy (2); inclusion body myositis (2); laminopathy (2); Liver Dysfunction (2); metastatic tumor (2); myotonic dystrophy type 1 (2); acute tubular necrosis (1); albinism (1); amyotrophic lateral sclerosis (1); aortic atherosclerosis (1); auditory neuropathy (1); bacterial infection (1); bent spine syndrome (1); Bethlem myopathy (1); bladder urothelial carcinoma (1); bone marrow failure syndrome (1); breast carcinoma (1); breast invasive carcinoma (1); Camptocormia (1).
A further 41 diseases each share a sentence with DYSF in 1 paper.